ALB (albumin)
Diseases named in the same sentence as ALB in open-access papers (continued):
Sharing a sentence is not in itself a finding about the gene and the disease.
Hypertension (continued). "A large number of studies have identified various risk factors of AKI occurrence in AMI, including advanced age, hypertension, DM, CKD, anemia, severe Killip class, tachycardia at presentation, longer reperfusion time, decreased serum albumin and more contrast used." (PMID 33781208, 2021). "Univariate analysis demonstrated that operative time, duration of anesthesia, age, hypertension, serum albumin, and PNI differed between the PD and non-PD groups (P < 0.05)." (PMID 34511076, 2021). "Additional criteria that differentiated the type of CDS alert received by a provider included the presence of uncontrolled hypertension and an increased level of or lack of a recent albumin/creatine ratio." (PMID 34071920, 2021). "Age, pre-existing conditions (cardiac disease, hypertension, and more than two comorbidities), and 1st Laboratory detection (WBC, NEU, LYM%, NEU%, NLR, FIB, CRP, TBIL, ALB, GRF, CK-MB, Myoglobin, and Troponin) were identified as the predictors of the severity of disease by univariate analysis." (PMID 32582575, 2020). "Compared with participants without hypertension, those with hypertension were more likely to be older, to have higher weight, creatinine, haemoglobin, albumin and phosphate levels (all p < 0.043)." (PMID 32188410, 2020). "Accumulating evidence suggests that in the sodium-sensitive type of essential hypertension, glomerular capillary pressure is elevated, and urinary albumin excretion is greater than that in the non-sodium-sensitive type." (PMID 32213948, 2020). "MCNS patients with AKI are characterized by increased urinary protein excretion, reduced serum albumin, older age and hypertension at presentation compared with patients without AKI." (PMID 29179690, 2017). "This suggests that in immunocompromised mice albumin leakage is not induced by systemic hypertension, but by increased permeability of the glomerular filtration membrane or an increase in glomerular hydrostatic pressure." (PMID 28482823, 2017). "Angiotensin-II (AngII) infusion in SCID (severe combined immunodeficiency) mice resulted in lower SBP, albumin excretion and renal damage than in wild-type mice and hypertension was not maintained after subtotal nephrectomy in athymic mice." (PMID 28482823, 2017). "When compared with subjects in Q1 group, those with higher homocysteine levels were more likely to be older, male, and current smokers, and they tended to have increased prevalence of hypertension as well as higher levels of BMI, ALT, TBIL, ALB, serum uric acid, TG, hs-CRP and creatinine." (PMID 27955646, 2016). "Remission with either mode of treatment was not related to sex (p=0.96), age (p=0.54), serum albumin (p=0.37) or hypertension (p=0.43)." (PMID 28293374, 2016). "Remission was not related to sex (p=0.96), age (p=0.54), serum albumin (p=0.37) or hypertension (p=0.43) but to serum cholesterol (p= 0.02)." (PMID 28293374, 2016). "As for disease status, older adults with respiratory and liver disease had lower serum albumin levels than did those with no disease, and serum albumin was higher in older adults with hypertension and hyperlipidemia." (PMID 27276092, 2016). "By univariate analysis, age, male sex, admission NIHSS score, excess alcohol consumption, hypertension, GGOs in chest CT images, PaO2/FiO2, APACHE II score, albumin, corticosteroid therapy with response, and IMV support were significantly (p values < 0.05) associated with hospital mortality." (PMID 26864571, 2016). "Our findings in a retrospective cohort of essential hypertensive patients revealed lower serum albumin levels in non-dippers than dippers." (PMID 27276394, 2016). "Our findings indicate that serum albumin levels, rather than albuminuria, are a significant determinant of nighttime BP decline, at least among non-diabetic essential hypertensive patients with moderate proteinuria." (PMID 27276394, 2016).
Hypertension (continued). "Our findings emphasize the importance of serum albumin levels, rather than urinary albumin excretion, as an independent predictor of nocturnal systolic dipping, at least in non-diabetic essential hypertensive patients with moderate proteinuria." (PMID 27276394, 2016). "The preservation of renal structure and function, and subsequent increase in plasma albumin, may have been due to the downregulation of Agt mRNA expression and the accompanying decrease in SBP in HIIT, as hypertension is directly related to renal damage." (PMID 26090382, 2015). "Multivariate Cox regression analysis showed that low serum albumin, the presence of hypertension, high serum IL-18, and less negative GLS (>−15%) were independently associated with all-cause mortality." (PMID 24599060, 2014). "In the present study, urinary albumin excretion was associated with a high IOP of ≥18 mmHg, independent of age, gender, hypertension, BMI, dyslipidemia, blood glucose level, region of habitation, and education level." (PMID 24788677, 2014). "In patients with albumin: creatinine ratio ≥ 70 mg/mmol with or without hypertension or cardiovascular disease, Angiotensin Converting Enzyme inhibitors or Angiotensin Receptor Blockers should be prescribed." (PMID 24955116, 2014). "The association between HD and risk of NODM was independent of patient’s age, gender, comorbid hypertension, hematocrit, and serum albumin." (PMID 24504072, 2014). "Multiple logistic regression analysis was used to assess the relationship between log-transformed albumin/creatinine ratio (ACR) tertiles and an IOP of ≥18 mmHg after adjusting for age, gender, hypertension, body mass index, triglycerides, area of residence, and education level." (PMID 24788677, 2014). "Relaxin treatment had no influence on blood pressure, urinary albumin excretion, or mortality in the dTGR model of hypertension-induced target-organ damage." (PMID 24710077, 2014). "For the stable hemodialysis patients, decreased albumin level, hypertension, increased serum IL-18 level, and less negative GLS were the independent prognostic predictors." (PMID 24599060, 2014). "Individuals with BMI ≥ 25 kg/m2 OR = 2.28(1.13-4.6) and lower MMI OR = 13.4 (5.21-34.56) showed greater chances of high UA levels even after all adjustments (gender, age, CRP, gamma-gt, LDL, creatinine, urea, albumin, HDL-c, TG, arterial hypertension and glucose)." (PMID 23311699, 2013). "There were no adverse events such as congestive heart failure, hypertension, or allergic reaction to human albumin/furosemide after both treatments in this study." (PMID 22931630, 2012). "Neutrophil percentage‐to‐albumin ratio (NPAR) is an easily obtainable composite index of systemic inflammation with prognostic value in cardiovascular disease, but its utility for primary stroke prevention in hypertension remains unclear." (PMID 41543379, 2026). "However, individuals with a higher CRP/albuminratio tended to have a more severe DFI, a higher incidence of hypertension, andhigher WBC and platelet counts, neutrophil percentage, and fasting glucose,HbA1c, and CRP levels but lower RBC, hemoglobin, and albumin levels (P <0.05)." (PMID 40622101, 2025). "However, the relationship between serum albumin and cardiovasculardeath was only observed in individuals without hypertension (T2 vs T1, HR: 0.480,95% CI: 0.249–0.923, p < 0.05), and not in T3, which should be notedto avoid misinterpretation." (PMID 40927110, 2025). "Thus, there was an increase in albumin excretion in those with low eGFR without hypertension (SBP/DBP of 130/80 mm Hg)." (PMID 40863329, 2025). "However, Klotho levels exhibited no significant impact on participants’ weight (BMI), serum albumin, cholesterol, serum phosphorus, blood calcium, history of hypertension, history of coronary heart disease, or history of smoking." (PMID 38287280, 2024).
Hypertension (continued). "The positive correlation between ALB and IR prevalence could be observed in older persons, Black persons, and those with hypertension, and a negative correlation was only found in those with a BMI ≥ 25 kg/m2." (PMID 39345890, 2024). "The analysis of risk factors indicated that the age of NS onset, rather than the age of admission, sex, serum albumin level, response to steroid treatment, infection, hypertension, and nephrotoxic drug application, were all significantly associated with the incidence of AKI." (PMID 39759881, 2024). "This showed that the relationship between these parameters was linear, rather than curved, after adjustment for age, hypertension, nuclear fragmentation, mesangial cell and matrix proliferation, microthrombi, ALB, serum C3, 24-hour proteinuria, endothelial hyperplasia, and Hb." (PMID 39719070, 2024). "For essential hypertension, the observed flow rates were 1.7–9644.74 cc/h for 0.9% normal saline, 3.4–9324.61 cc/h for Hartmann’s solution, 3.84–9474.83 cc/h for the plasma solution, 9.91–4462.15 cc/h for 6% hetastarch, and 9.87–6327.75 cc/h for 5% albumin." (PMID 39685067, 2024). "In addition, in vivo studies in a mouse model of PE demonstrate that CALCA treatment protects from the development of sFLT-1-induced PE-like symptoms such as hypertension, ATII hypersensitivity, the elevated albumin–creatinine ratio, and fetal growth restriction." (PMID 37719463, 2023). "However, covariates were only adjusted for age and smoking history in their work, with the lack of other potential covariate such as hypertension, serum albumin and so on13–15." (PMID 37336896, 2023). "Moreover, levels of SBP, DBP, serum albumin, baseline 25(OH)D, TC, LDL-C, serum calcium, serum creatinine, eGFR, serum IgG, serum C4, the ratio of hypertension, and the number of VD receivers were significantly different between any two of the three groups (P < 0.05)." (PMID 37181155, 2023). "According to whether age ≥ 70 years, ECOG ≥ 2, aa‐IPI scores ≥ 2, B symptoms, body mass index (BMI) ≥ 25,16 hypertension or cardiovascular disease, double‐express, elevated β2‐MG, elevated LDH, albumin ≤35 g/L, we divided the whole study population into subgroups." (PMID 36200320, 2023). "Adults with DR (n = 641) were more likely to be older, male, of other races, with lower education level, alcohol consumption, serum total cholesterol, and serum albumin, as well as having higher BMI, glycohemoglobin, and prevalence of hypertension and CHF than adults without retinopathy (n = 4,579)." (PMID 36388275, 2022). "The patients with physical dysfunction in both the early and established RA groups were older and had more active RA disease, more comorbidities (except hypertension in early RA), and a lower level of serum albumin compared with those without physical dysfunction." (PMID 36505248, 2022). "In this retrospective observational study, a negative correlation between PC ratio and risk of moderate-to-severe pneumonia was found, independent of likely confounders, including age, gender, hypertension, total protein, albumin, lactic dehydrogenase, and lymphocyte." (PMID 35592303, 2022). "Finally, our study evaluated the influence of BMI, DM, and hypertension on PCa, but did not include other components of metabolic syndrome, such as lipids and albumin." (PMID 35903679, 2022). "The serum levels of γ-glutamyl transpeptidase (GGT) (P = 0.026), albumin (ALB) (P = 0.018), and A/G (albumin/globulin) (P = 0.022) levels and blood urea nitrogen (BUN) (P = 0.021) were significantly different between hypertension patients and non-hypertension patients." (PMID 36326681, 2022). "In non-diabetic population, strategies to decrease the development of new-onset hypertension, resting heart rate, body mass index, fasting glucose, total cholesterol, and GPT and increase serum albumin level might be helpful in slowing the longitudinal change of HbA1c." (PMID 34357115, 2021).
Hypertension (continued). "Moreover, we demonstrated that an older age, female, not living alone, single marriage status, low education, no drinking, hypertension, abnormal blood TG and albumin levels were independently correlated with cognitive decline." (PMID 34475488, 2021). "Compared to baseline data, age, prevalence of hypertension, systolic and diastolic blood pressures, heart rate, BMI, fasting glucose, HbA1c, serum creatinine, total cholesterol, triglyceride, GOT, and GPT were increased and uric acid and albumin were decreased at follow-up." (PMID 34357115, 2021). "The local team opted to include the one-time notification alert but combined it with the alert for APOL1-positive patients with a normal albumin/creatinine ratio and hypertension, which provided the same general recommendation and did not present follow-up actions." (PMID 34071920, 2021). "In addition to visual impairment, we found that an older age, female, not living alone, single marriage status, low education, no drinking, hypertension, abnormal blood TG and albumin levels were independently correlated with cognitive decline." (PMID 34475488, 2021). "Similarly, hypertensive patients had slight increase in mean albumin, creatinine, urea, potassium, and phosphorus levels than patients without hypertension." (PMID 31233556, 2019). "Moreover, the predictability of RAS blockade usage was reduced but near significant (adjusted OR, 0.65; 95% CI, 0.39–1.08) after adjustment for gender, age, CKD stage, observation time, DM, hypertension, CAD, antilipid agent use and the levels of albumin, Hct, and UPCR." (PMID 26469913, 2015). "Evaluation of hypertension organ damage was done locally at each site and no centralized reading or specific quality control of original examinations (including ultrasound scans, serum creatinine, and urinary albumin) was planned." (PMID 26347187, 2015). "Notably, in the female population, identical preoperative persistent hyperglycemia was associated with a higher incidence of prolonged LOS in patients without hypertension, cerebrovascular disease, and a history of stroke, who also had an albumin level > 35 g/L (P < 0.05)." (PMID 40660150, 2025). "The lactate/albumin ratio was significantly associated with increased ICU all-cause mortality in subgroups defined by age < 65 years, age ≥ 65 years, female and male sex, presence and absence of hypertension, as well as presence and absence of cardiovascular disease." (PMID 39685564, 2024). "Hence, strategies to decrease the development of new-onset hypertension, resting heart rate, BMI, fasting glucose, total cholesterol, and GPT and increase serum albumin level might be helpful in practice for slowing the longitudinal change of HbA1c in non-diabetic population." (PMID 34357115, 2021). "Moreover, the UACR, measured in a spot urine sample, is highly correlated with 24-h urine albumin excretion as a predictor of the development and progression of diabetic and non-diabetic renal diseases, as well as of incident hypertension and cardiovascular mortality." (PMID 34736407, 2021). "Although there are no reports about lysyl groups of albumin involved in hypertension, its lower level in interstitial fluid in our hypertensive group may also indicate a higher degree of oxidative stress associated with hypertension, as previous findings have suggested." (PMID 33187152, 2020). "The significantly lower nighttime systolic and diastolic BP in the Q2, Q3 and Q4 serum albumin quartiles in our cohort suggest that a decline in albumin levels beyond 4.1 g/dL appears to increase the likelihood of non-dipping status in patients with essential hypertension." (PMID 27276394, 2016). "The results of the Lasso regression model showed that the optimal λ = 0.0613281301006316 was used to screen for five nonzero coefficient-related indices of weaning failure: hypertension, SOFA score, tidal volume, respiratory rate, and serum albumin." (PMID 40225039, 2025).
Hypertension (continued). "After conducting a thorough subgroup analysis, the authors found that age, BMI, hypertension, UPRO, ALB, and severe nephrotic syndrome do not function as effect modifiers in influencing the association between the TG/HDL-C ratio and TA." (PMID 38327562, 2024). "The results consistently indicated that patients in the SCI group were more likely to be older and to have complicated hypertension, NEU, MONO, CRP, ESR, and PLT than were those in the No-SCI group, while LYM, HGB, and ALB were more common in the No-SCI group." (PMID 38565845, 2024). "The difference in tolerance of IV albumin in our patients and ALISAH is probably attributed to existing fluid overload in our patients due to induced hypervolemia with or without induced hypertension for the treatment of cerebral ischemia." (PMID 39553040, 2024). "Although parameters such as IBM, patient age, operative time, tumor classification, coronal artery disease, hypertension, neck dissection, COPD and albumin showed significance in single testing, it did not have a significant impact in the regression model." (PMID 37658335, 2023). "The results showed that the Gensini score was positively correlated with NHR,neutrophils, creatinine, LDL-C, sex, age, cigarette smoking, hypertension, there was a negative correlation between Gensini score and HDL-C, as well as albumin." (PMID 33676400, 2021). "Regression model with adjustments for age, VAT, HDL, LDL, urine albumin/creatinine, liver fat, GFR, gender, hypertension yes/no and glycemic status." (PMID 32074103, 2020). "However, age and the proportion of subjects with self-reported smoking, hypertension and antihypertensive treatment, and the mean systolic and diastolic blood pressures, were higher among subjects with microalbuminuria compared to subjects with non-detectable urine albumin." (PMID 32758145, 2020). "Treatment did not attenuate the development of hypertension when compared to vehicle‐treated SLE mice; however, urinary albumin excretion was lower in CYC‐treated animals." (PMID 31124322, 2019). "Our findings emphasize the importance of serum albumin levels, rather than UAE, as an independent predictor of nocturnal systolic dipping, at least in non-diabetic essential hypertensive patients with moderate proteinuria." (PMID 27276394, 2016). "The goal of this study was to evaluate the relationship between serum albumin levels and 24-hour ambulatory blood pressure monitoring (24-h ABPM) recordings in non-diabetic essential hypertensive patients." (PMID 27276394, 2016). "These patients also exhibited a higher prevalence of hypertension, higher systolic blood pressure, and increased waist circumference, HbA1c level, HDL-c level, and urinary albumin/creatinine ratio compared with those without DR." (PMID 25856787, 2015). "Survivors compared to non-survivors were more likely to have hypertension; higher mean MMSE scores; higher serum albumin levels; and lower mean serum levels of CRP, IL-6, and ET-1." (PMID 26289439, 2015). "Compared with non-DN patients, DN patients more frequently had hypertension, cardiovascular disease, and stroke, as well as presented with a higher BMI, eGFR, and CRP, but a lower DBP, MAP, and serum albumin." (PMID 23585903, 2013). "Multivariate logistic regression identified nine independent risk factors for postoperative pneumonia, including lower preoperative albumin level, older age, male, smoker, ASA > II, combined heart disease, more fluid infusion, longer surgical duration and absence of hypertension." (PMID 41200138, 2025). "Furthermore, both human and animal studies consistently report microalbuminuria, elevated albumin-to-creatinine ratios, and reduced GFR in subjects consuming HFD or a Western diet, independent of DM and hypertension." (PMID 39765652, 2024).